KRT10 (keratin 10)
Description:
Structural component of intermediate filaments in suprabasal keratinocytes of stratified epithelia. Forms heteropolymers primarily with the type II keratin KRT1, and also with KRT2, assembling into intermediate filament networks that support terminal differentiation, mechanical resilience, and epidermal barrier formation. (Microbial infection) Acts as a mediator of S.aureus adherence to desquamated nasal epithelial cells via clfB, and hence may play a role in nasal colonization. (Microbial infection) Binds S.pneumoniae PsrP, mediating adherence of the bacteria to lung cell lines. Reduction of levels of KRT10 keratin decrease adherence, overexpression increases adherence. Neither protein has to be glycosylated for the interaction to occur.
Synonyms: K10; KPP; CK10; BCIE; BIE; EHK; EHK2; EHK2A; EHK2B; IHL
Tractability: Antibody: UniProt places it where antibodies can reach, with high confidence; its Gene Ontology location is reachable by antibodies, with high confidence. PROTAC: ubiquitination databases record sites on it.
Gene: Protein-coding gene on chromosome 17 (40,818,117 to 40,822,614, reverse strand). Ensembl gene ENSG00000186395.
Subcellular location: Secreted, extracellular space; Cell surface; Cytoplasm
Pathways (Reactome):
Developmental Biology: Differentiation of Keratinocytes in Interfollicular Epidermis in Mammalian Skin; Formation of the cornified envelope; Keratinization
Gene Ontology:
Molecular function: protein binding; protein heterodimerization activity; structural constituent of skin epidermis; structural molecule activity
Biological process: cornification; keratinocyte differentiation; protein heterotetramerization; intermediate filament organization; morphogenesis of an epithelium; positive regulation of epidermis development
Cellular component: cell surface; cornified envelope; cytoplasm; extracellular exosome; extracellular region; keratin filament; membrane; nucleus; cytoskeleton; cytosol; intermediate filament
Genetic constraint (gnomAD): Loss-of-function variants: 38 observed, 56.52 expected, observed/expected ratio (o/e) 0.67, 90% interval 0.52 to 0.88. The upper end of that interval is the gene's LOEUF score, 0.88, which puts it in group 3 of 6, group 1 being the genes least tolerant of losing a copy. Missense variants: 701 observed, 721.08 expected, observed/expected ratio (o/e) 0.97, 90% interval 0.91 to 1.03. Synonymous variants: 330 observed, 297.39 expected, observed/expected ratio (o/e) 1.11, 90% interval 1.01 to 1.22.
Homologues: Orthologues: chimpanzee KRT10 (93% identical), macaque KRT10 (91% identical), dog KRT10 (84% identical), mouse Krt10 (81% identical), rat Krt10 (80% identical), pig KRT10 (80% identical), rabbit KRT10 (73% identical). Paralogues in human: KRT14 (47% identical), KRT9 (47% identical), KRT16 (47% identical), KRT24 (47% identical), KRT27 (45% identical), KRT28 (45% identical), KRT15 (45% identical), KRT12 (44% identical), KRT25 (44% identical), KRT26 (44% identical), KRT13 (44% identical), KRT17 (43% identical), and 56 more.
Diseases named in the same sentence as KRT10 in open-access papers:
KRT10 is named in the same sentence as 143 diseases in open-access papers, as found by Europe PMC text mining. Sharing a sentence is not in itself a finding about the gene and the disease. The quoted sentences say what the papers report.
epidermolytic ichthyosis (33 papers, 2013 to 2025). A rare keratinopathic ichthyosis (KPI), that is characterized by a blistering phenotype at birth which progressively becomes hyperkeratotic. "While epidermolysis bullosa was initially suspected, immunofluorescence antigen mapping and genetic testing confirmed epidermolytic ichthyosis, with a heterozygous pathogenic variant in the KRT10 gene (c.467G>A, p.Arg156His)." (PMID 40741111, 2025). "Disruption of KRT10 function can compromise epidermal integrity and cause abnormal cornification as in patients with KRT10 mutations in epidermolytic ichthyosis." (PMID 37561594, 2023). "For example, KRT1 and KRT10 have been associated with epidermolytic hyperkeratosis (EHK), an ichthyosis that is hallmarked by thick hyperkeratotic skin." (PMID 35900871, 2022). "Dominant negative mutations of the genes that encode keratin 1 and 10 (KRT1, KRT10) cause epidermolytic ichthyosis (EI), previously also known as epidermolytic hyperkeratosis and bullous congenital ichthyosiform erythroderma of Brocq." (PMID 33562614, 2021). "For example, mutations in KRT5 or KRT14 are implicated in epidermolysis bullosa simplex, and KRT1 or KRT10 dysfunction causes bullous congenital ichthyosiform erythroderma; moreover, fragile skin structure is observed in almost all such conditions." (PMID 31581253, 2019). "Some authors suggest that the response to retinoids should also be influenced by the causal gene: patients with epidermolytic ichthyosis caused by a KRT10 mutation responding better than those with a KRT1 mutation." (PMID 29618363, 2018). "In this regard, it is intriguing to consider epidermolytic hyperkeratosis patients and mice, which harbor suprabasal epidermal keratin one and/or keratin 10 mutations." (PMID 30520726, 2018). "KRT1 and KRT10 are known to play a role in maintaining the integrity of the epidermis and are mutated in other blistering diseases such as epidermolytic ichthyosis." (PMID 24497829, 2014). "Due to its classic role in the epidermis development, mutations in KRT10 were associated with epidermolytic hyperkeratosis." (PMID 23671866, 2013). "First, it is well-established that mosaic mutations can be passed on to offspring as germline heterozygous disease, for example, epidermal naevi with keratin 1 gene K1 and keratin 10 gene K10 mutations passed on as epidermolytic ichthyosis or mosaic NF1 being passed down as germline NF1." (PMID 36566878, 2023). "Genetic variants in KRT1 or KRT10 in humans typically present with an epidermolytic ichthyosis." (PMID 36251712, 2022). "KRT10 is required for epidermal integrity, as KRT10 mutation leads to epidermolytic hyperkeratosis." (PMID 24809979, 2014). "Mutations in KRT1 or KRT10 are associated with EI, but also contribute to related disorders such as ichthyosis Curth‐Macklin, annular epidermolytic ichthyosis, ichthyosis with confetti, autosomal recessive and nevoid forms." (PMID 40741111, 2025). "The genes KRT10 and KRT1 are expressed in keratinocytes during early differentiation, and their mutations cause epidermolytic hyperkeratosis." (PMID 37106791, 2023). "Epidermolytic hyperkeratosis or epidermolytic ichthyosis (EI, OMIM 113800) is an uncommon keratinization disorder which affects approximately 1:200000 infants and is caused by pathogenic heterozygous variants in the genes KRT1 and KRT10." (PMID 40741111, 2025). "Bullous congenital ichthyosiform erythroderma (BCIE, OMIM 113800), also known as epidermolytic hyperkeratosis (EH) and now classified inside the class of Keratinopatic Ichthyoses, is an autosomal dominant disorder of the skin associated to mutations in KRT1 and KRT10 genes." (PMID 34199056, 2021).
epidermolytic ichthyosis (continued). "The KRT1-related epidermolytic hyperkeratosis presents with or without palmo-plantar keratoderma, while KRT10-related epidermolytic ichthyosis typically does not involve palmo-plantar keratoderma." (PMID 36251712, 2022).
psoriasis (33 papers, 2011 to 2026). An autoimmune condition characterized by red, well-delineated plaques with silvery scales that are usually on the extensor surfaces and scalp. "In psoriasis, various pathogenic mutations in KRT10 have been identified in affected skin lesions, which indicates its involvement in the pathogenesis of psoriasis." (PMID 38606161, 2024). "qPCR results revealed significantly increased expression of Lcn2, Tnfsf12, Il1b, Krt5, and Krt10 mRNA in the skin of Fn14–/– mice with IMQ-induced psoriasis." (PMID 40369189, 2025). "Lachnoclostridium was positively correlated with keratin 10, indicating its suppressive effect on psoriasis." (PMID 37111171, 2023). "As a further confirmation, Tp63 mRNA and KRT10 mRNA expression were significantly up‐regulated in ozone‐treated psoriasis lesions; Tp63 and KRT10 mRNA expression in tissue samples was positively correlated." (PMID 32168425, 2020). "To further confirm that KRT6 and KRT10 are involved in the effects of the ozone therapy on psoriasis, we established psoriasis‐like dermatitis model in mice by applying IMQ cream." (PMID 32168425, 2020). "In the present study, KRT6, IL‐17 and IL‐22 protein within psoriasis lesions was decreased, while KRT10 and Tp63 protein in psoriasis lesions was increased by ozone treatment in both patient and IMQ mice psoriatic tissues." (PMID 32168425, 2020). "KRT6, IL‐17 and IL‐22 protein within psoriasis lesions was significantly decreased, while KRT10 protein in psoriasis lesions was increased by ozone treatment." (PMID 32168425, 2020). "As we have mentioned, KRT10 expression is significantly down‐regulated in psoriasis lesions while rescued by ozone treatment." (PMID 32168425, 2020). "To assess whether CR influences epidermal barrier in the skin of mice with IMQ-treated psoriasis, we examined the mRNA expression levels of Krt14, Krt10, Lori, Fila and Inv by RT-PCR." (PMID 39371941, 2024). "In conclusion, the application of ozonated oil could be an efficient and safe treatment for psoriasis; ozone promotes the differentiation of keratinocytes via increasing Tp63‐mediated transcription of KRT10, therefore improving psoriasis." (PMID 32168425, 2020). "In conclusion, the application of ozonated oil could be an efficient and safe treatment for psoriasis; ozone promotes the differentiation of basal keratinocytes via increasing Tp63‐mediated transcription of KRT10, therefore improving psoriasis." (PMID 32168425, 2020). "Tp63 and KRT10 mRNA expression could be remarkably up‐regulated upon ozone treatment in psoriasis lesions, compared to those in non‐treated psoriasis lesions." (PMID 32168425, 2020). "In comparison with normal samples, the glycolysis score was significantly higher in psoriasis samples in KRT5+ KRT14+ KC, KRT1+KRT10+ KC, and LDHA+SLC2A1+ KC (all P<0.001)." (PMID 37205116, 2023). "To confirm that skin damage and psoriasis were induced in our AD-HSE, we examined KRT10 and KRT16 expression." (PMID 35216228, 2022). "We further examined the expression of early differentiation markers such as cytokeratin 10 (CK10) and cytokeratin 1 (CK1) from healthy skin and the psoriasis lesion in transgenic mice and found it markedly increased compared to that of control littermates." (PMID 30219085, 2018). "Notably, mRNA expression level of IL-38 was negatively related to psoriasis area and severity index (PASI) and IL-17A, but positively correlated with cytokeratin 10 (CK10) expression." (PMID 34539413, 2021). "To provide further evidence, we examined Tp63 and KRT10 expression in psoriasis lesion tissues with or without ozone treatment." (PMID 32168425, 2020). "The excessive proliferation and the differentiation of basal keratinocytes have been considered critical issues during pathological psoriasis process, in which keratin 6 (KRT6) and KRT10 might be involved." (PMID 32168425, 2020).
psoriasis (continued). "Our results showed that administration of gentamicin alleviated pathogenesis of psoriasis-like symptoms, including alleviating psoriasiform skin inflammation, a decrease in the skin epidermis thickness, decreasing mRNA expression of IL-17A, IL-23, S100A7, and increased mRNA expression of KRT10." (PMID 36710269, 2023). "Finally, the mRNA expression of Tp63 and KRT10 was examined in psoriasis lesion tissues with or without ozone treatment; we examined the interaction between the expression of Tp63 and KRT10 within tissues using Pearson's correlation analysis." (PMID 32168425, 2020).
ichthyosis (12 papers, 2015 to 2025). Disorders of cornification that are characterized by visible scaling and/or hyperkeratosis of most or all of the skin. "Other dog models for human non-syndromic ichthyoses include Norfolk Terriers with an epidermolytic ichthyosis caused by a KRT10 variant, Bulldogs with ARCI caused by a NIPAL4 variant, and Jack Russell Terriers with another form of ARCI caused by a TGM1 variant." (PMID 28249031, 2017). "Intriguingly, ichthyosis with confetti, a skin disease characterized by confetti-like appearance of revertant skin spots, is associated with a mutation in Keratin 10, which, due to its nucleolar mislocalization, could affect ribosome production similar to M−/+ mutants." (PMID 26212135, 2015). "The clinical and histological resemblance between EHK and inherited ichthyoses point to a possible role of functional mutations in genes encoding KRT1 and KRT10, which are essential for epidermal differentiation in the spinous layer." (PMID 39797176, 2024). "CRIE, also known as ichthyosis with confetti, is a peculiar non-blistering KI subtype caused by dominant negative mutations in KRT10 or, less commonly, KRT1." (PMID 33081034, 2020). "Finally, keratinopathic ichthyoses, the third category of non-syndromic ichthyoses, are caused by variants in the KRT1, KRT2, or KRT10 genes." (PMID 28249031, 2017). "Single gene selection to a normal phenotype may be found in patients exhibiting ichthyosis with mottling due to dominant KRT1 and KRT10 mutations, in which numerous clones of normal skin arise because of increased viability of cells that have converted to the homozygous wild type gene." (PMID 34284807, 2021). "Since the phenotype of patchy erythema and ichthyosis was already described in the literature, as correlated to mutations in KRT1 and KRT10 genes, we sequenced these genes as well, but no mutations were found." (PMID 37762265, 2023).
Hyperkeratosis (11 papers, 2013 to 2025). Hyperkeratosis is a histopathological term defining a thickened stratum corneum and may be present in many different skin conditions, with many possible overlaps. "Altered KRT1/KRT10 dimer formation due to variants affecting the structure of the paired 2B and V2 domains leads to severe acanthosis and hyperkeratosis in humans, reflecting the histologic features observed in the affected Chinese shar-pei." (PMID 36251712, 2022).
melanoma (11 papers, 2015 to 2025). A malignant, usually aggressive tumor composed of atypical, neoplastic melanocytes. "Increased expression of KRT10 is correlated with the T stage as well as the tumor stage in melanoma." (PMID 33441834, 2021). "In our study, we found that KRT10 is highly expressed in primary melanoma than metastatic melanoma." (PMID 33441834, 2021). "A smaller tissue from patient ID 9561, collected in 2008, had four clusters, including melanoma (PMEL, TYRP1), immune cells (TMSB4X, IL32), keratinocytes (KRT10, KRT1, DSG1), and fibroblast areas (COL1A2, COL1A1, DCN)." (PMID 39846232, 2025). "The enrichment of these categories reflects the dysregulation of transcriptional programs typical of keratinocytes (e.g., SPRR1/2/3, KRT10/KRT16, LOR, IVL, EVPL, SCEL, TGM1/TGM3, CERS3, ACER1, DSP) and, above all, the epithelial crosstalk that influences melanoma biology." (PMID 41465101, 2025). "Several of the EMT-related genes with higher expression in NR patients encoded for molecules controlling adhesion (ITGB3, VCAM1, collagens, and others), interaction with extracellular matrix (VEGFA, MMP14, WNT5A, LAMA1, and others), and melanoma de-differentiation (KRT9, KRT10, EGFR, and others)." (PMID 37739939, 2023).
squamous cell carcinoma (8 papers, 2006 to 2026). A carcinoma arising from squamous epithelial cells. "Cytokeratin 10, another protein that is specifically expressed in cornifying squamous epithelium, has also been found to be preferentially expressed in low grade squamous cell carcinomas." (PMID 38961454, 2024). "Additionally, a 3D culture system using human squamous carcinoma cells (TR146) was used to evaluate and correlate the changes in the expression of type XVIII collagen gene, COL18A1, and epithelial keratinization-related markers, e.g., keratin 1 (KRT1) and 10 (KRT10)." (PMID 31554264, 2019).
viral infection (8 papers, 2014 to 2025). "We found that there was a reduction of both Krt10 and Fabp5 RNA levels in the MmuPV1-induced tail tumors 21 days after viral infection." (PMID 34343212, 2021). "Similarly, orf virus infection of the human 3D skin model also induced a downregulation of KRT10 transcription, as well as KRT1 and loricrin, 8 or 10 days post-infection." (PMID 40694389, 2025).
breast cancer (7 papers, 2008 to 2025). A primary or metastatic malignant neoplasm involving the breast. "In human breast cancer, high expression levels of KRT10, HECTD3, NSD3, and STOML2 were associated with unfavorable outcomes, whereas high BTN1A1 expression was linked to a better prognosis." (PMID 40839607, 2025). "Moreover, gene expression analysis indicated that high KRT10 levels were associated with shorter relapse-free and overall survival times in breast cancer." (PMID 40839607, 2025). "To determine if Wnt5a could affect the markers associated with basal mammary cancers, we used western blot analysis to determine the level of expression of several markers including K6, K5, K14, Sca-1, K8, and keratin 10 (K10)." (PMID 25401739, 2014). "While, other phosphoproteins (e.g., BTN1A1, KRT10, HECTD3, NSD3, and STOML2) were associated with human breast cancer prognosis." (PMID 40839607, 2025). "Furthermore, KRT10 may be a tumor differentiation marker, with 16% of patients with breast cancer testing positive for it." (PMID 40839607, 2025). "Many of these are enzymes or cytoskeletal proteins (ANXA1, KRT10, KRT16, TUBB, ACTB, ACTA1, PKM2, and HSPA8) that have been previously reported as able to induce autoantibodies with diagnostic potential across different tumor types, including PDAC, breast cancer, and neuroblastoma." (PMID 30651550, 2019). "A few of NETs-related genes are highly expressed in breast cancer, such as ACTB, ACTG1, KRT10." (PMID 37304069, 2023).
papilloma (7 papers, 2010 to 2023). A benign epithelial neoplasm that projects above the surrounding epithelial surface and consists of villous or arborescent outgrowths of fibrovascular stroma. "The increased expression of KRT14, accompanied by reduced expression of KRT10, in the Mcpip1eKO papillomas indicated the acquisition of a more aggressive phenotype." (PMID 34903245, 2021). "Immunohistochemical analysis of differentiation layer markers cytokeratin 14 (K14) and cytokeratin 10 (K10) was used to assess the differentiation state of papillomas in comparison with normal uninfected skin." (PMID 28107544, 2017). "Examination of keratin 10 and 13 expression of the mouse tumors showed that K10 expression was strong in papilloma while there was moderate staining in the keratoacanthomata." (PMID 23977171, 2013). "Compared with those in the control mice, the papillomas in Mcpip1eKO mice showed increased expression levels of KRT14; in contrast, KRT10 expression was clearly reduced." (PMID 34903245, 2021).
cyst (6 papers, 2014 to 2025). A sac-like closed membranous structure that may be empty or contain fluid or amorphous material. "In cKO mice, a premature induction of Krt1 expression was observed at P14, and it persisted throughout the cyst formation, whereas less pronounced effects on Krt10 expression were observed at P14 to P18." (PMID 35247391, 2022). "Following marsupialization for decompression, interleukin-1 and cytokeratin 10 which are important in cyst expansion are dissipated." (PMID 24790606, 2014). "In addition, a proliferation of Krt10-positive cyst-forming keratinocytes may be a concern." (PMID 39796272, 2025).